SNORA1B (small nucleolar RNA, H/ACA box 1B)
Gene: Small nucleolar RNA gene on chromosome 8 (55,902,723 to 55,902,855, reverse strand). Ensembl gene ENSG00000199405.
Gene Ontology:
Biological process: RNA processing
Cellular component: nucleolus
Homologues: Orthologues: chimpanzee SNORA1B (98% identical), macaque SNORA1B (95% identical), mouse Gm22620 (83% identical), rat Snora1b (77% identical). Paralogues in human: SNORA1 (95% identical).